KDSR (3-ketodihydrosphingosine reductase)
Description:
Catalyzes the reduction of 3'-oxosphinganine (3-ketodihydrosphingosine/KDS) to sphinganine (dihydrosphingosine/DHS), the second step of de novo sphingolipid biosynthesis.
Synonyms: FVT1; SDR35C1; DHSR; EKVP4
Tractability: Antibody: UniProt predicts a signal peptide or a membrane-spanning region. PROTAC: ubiquitination databases record sites on it; its protein half-life has been measured.
Gene: Protein-coding gene on chromosome 18 (63,327,566 to 63,367,615, reverse strand). Ensembl gene ENSG00000119537.
Subcellular location: Endoplasmic reticulum membrane
Pathways (Reactome):
Metabolism: Sphingolipid de novo biosynthesis
Gene Ontology:
Molecular function: 3-dehydrosphinganine reductase activity; protein binding; NADPH binding
Biological process: 3-keto-sphinganine metabolic process; ceramide biosynthetic process; glycosphingolipid biosynthetic process; sphingolipid biosynthetic process; sphingomyelin biosynthetic process; sphingolipid metabolic process
Cellular component: cytoplasmic side of endoplasmic reticulum membrane; endoplasmic reticulum; endoplasmic reticulum membrane; membrane; extracellular region
Genetic constraint (gnomAD): Loss-of-function variants: 8 observed, 14.96 expected, observed/expected ratio (o/e) 0.53, 90% interval 0.31 to 0.96. The upper end of that interval is the gene's LOEUF score, 0.96, which puts it in group 4 of 6, group 1 being the genes least tolerant of losing a copy. Missense variants: 204 observed, 228.59 expected, observed/expected ratio (o/e) 0.89, 90% interval 0.8 to 1. Synonymous variants: 80 observed, 81.87 expected, observed/expected ratio (o/e) 0.98, 90% interval 0.81 to 1.18.
Gene-disease validity (ClinGen):
ClinGen rates the evidence that KDSR causes each of these diseases.
erythrokeratodermia variabilis et progressiva 4 (autosomal recessive): Definitive.
Homologues: Orthologues: chimpanzee KDSR (100% identical), macaque KDSR (99% identical), dog KDSR (96% identical), pig KDSR (96% identical), rabbit KDSR (95% identical), mouse Kdsr (93% identical), rat Kdsr (93% identical), guinea pig KDSR (92% identical), tropical clawed frog kdsr (83% identical), zebrafish kdsr (81% identical), Caenorhabditis elegans Y37E11AM.3 (39% identical), Drosophila melanogaster Kdsr (36% identical). Paralogues in human: RDH13 (23% identical), DHRS13 (22% identical), RDH14 (21% identical), DHRSX (20% identical).
Diseases named in the same sentence as KDSR in open-access papers:
KDSR is named in the same sentence as 27 diseases in open-access papers, as found by Europe PMC text mining. Sharing a sentence is not in itself a finding about the gene and the disease. The quoted sentences say what the papers report.
spinal muscular atrophy (4 papers, 2017 to 2023). A motor neuron disease that affect the muscles, and characterized by muscle weakness and atrophy resulting from progressive degeneration and irreversible loss of the anterior horn cells in the spinal cord (i.e., lower motor neurons) and the brain stem nuclei. "Mutations of the gene encoding 3-ketodihydrosphingosine reductase (FVT1), which catalyzes the second step of de novo synthesis of ceramide, lead to spinal muscular atrophy (SMA) in cattle." (PMID 36836867, 2023). "Before the discovery of human mutations in KDSR, data linking this gene to disease have been very limited, aside from a missense variant in the bovine ortholog of KDSR that was proposed to cause spinal muscular atrophy." (PMID 28774589, 2017). "Moreover, a mutation in 3-ketodihydrosphingosine reductase (FVT1), which catalyzes the 2nd step in de novo ceramide synthesis, is associated with bovine spinal muscular atrophy." (PMID 29163032, 2017).
erythrokeratoderma (3 papers, 2017 to 2022). An umbrella term for a group of rare genetic skin disorders characterized by well-demarcated plaques of reddened, dry and thickened skin. "Whole-exome sequencing showed compound heterozygous mutations in KDSR, a candidate gene recently implicated in progressive symmetric erythrokeratoderma." (PMID 28774589, 2017). "One very recent discovery that expands the molecular pathology of ichthyosis has been the identification of mutations in KDSR in four individuals with clinical phenotypes of progressive symmetric erythrokeratoderma." (PMID 28774589, 2017). "In contrast, use of isotretinoin in individuals with KDSR mutations and a progressive symmetric erythrokeratoderma phenotype was reported to be very effective." (PMID 28774589, 2017). "Mutations in KDSR have recently been reported in inherited recessive forms of progressive symmetric erythrokeratoderma, but our study shows that biallelic mutations in KDSR are implicated in an extended spectrum of disorders of keratinization in which thrombocytopenia is also part of the phenotype." (PMID 28774589, 2017). "It was recently demonstrated that KDSR mutations causing structural and functional defects in KDSR, the next enzyme in sequence of de novo sphingolipid synthesis, have been shown to associate with the inherited skin disorder progressive symmetric erythrokeratoderma." (PMID 31632963, 2019). "At the beginning, Netherton syndrome and Erythrokeratoderma variabilis phenotypes were suspected, but no hair shaft abnormalities were found and no mutations in SPINK5 and EKV genes (GJB2, GJB3, GJB4, GJB6 and KDSR) were identified (data not shown)." (PMID 34983512, 2022).
B-cell lymphomas (2 papers, 2022 to 2025). "Additionally, it is known that some B-cell lymphomas can have mutations in FVT1 (KDSR), a gene that codes for 3-ketodihydrosphingosine reductase, which synthesizes dehydrosphinganine, a precursor of ceramide." (PMID 35565181, 2022).
Ewing sarcoma (2 papers, 2012 to 2023). A small round cell tumor that lacks morphologic, immunohistochemical, and electron microscopic evidence of neuroectodermal differentiation. "Other microsatellite-containing, direct EWS/FLI targets such as CACNB2, FEZV1, FCGRT, FVT1/KDSR, ABHD6 and KIAA1797 have also been identified, although the functional importance of these targets in Ewing sarcoma has not been determined." (PMID 24704979, 2012).
Palmoplantar keratoderma (2 papers, 2017 to 2021). Abnormal thickening of the skin of the palms of the hands and the soles of the feet. "A recent article reported the case of a Harlequin fetus-like newborn, who improved in the first weeks and presented with palmoplantar keratoderma and leukokeratosis anogenitalis caused by KDSR mutation." (PMID 34199106, 2021).
Thrombocytopenia (2 papers, 2017 to 2022). A reduction in the number of circulating thrombocytes. "Patients with mutations in KDSR also exhibit progressive thrombocytopenia and a moderate functional platelet defect that develops early in life." (PMID 28774589, 2017). "Moreover, we show that the KDSR mutations we identified are also associated with accompanying thrombocytopenia." (PMID 28774589, 2017).
breast carcinoma (1 paper, 2024). "In this interaction, KLHL18 has a tumor suppressor function, while KDSR is active through sphingolipid metabolism and its inhibition causes endoplasmic reticulum dysfunction specific to breast cancer cells." (PMID 38627780, 2024). "One of the first interactions that emerged in breast cancer tissue compared to normal tissue was the interaction between RMND5A, EIF5B, SUN2, KLHL18, KDSR, RPSK6KA3 ceRNAs and the miR-338-5p, miR-223-3p, miR-129-5p, miR-642a-5p, miR-3619-5p, and miR-382-5p miRNAs." (PMID 38627780, 2024).
congenital ichthyosis (1 paper, 2017). "Using whole-exome sequencing in four probands with undiagnosed skin hyperkeratosis/ichthyosis, we identified compound heterozygosity for mutations in KDSR, encoding an enzyme in the de novo synthesis pathway of ceramides." (PMID 28774589, 2017). "Although there are currently no data specifically implicating KDSR mutations as being any more likely to lead to increased infant mortality over other forms of congenital ichthyosis, this potentially poor outcome will need to be reviewed as more cases of KDSR mutations are documented." (PMID 28774589, 2017).
Hyperkeratosis (1 paper, 2017). Hyperkeratosis is a histopathological term defining a thickened stratum corneum and may be present in many different skin conditions, with many possible overlaps. "(2017) in showing that defective ceramide biosynthesis due to mutations in KDSR is responsible for some forms of local hyperkeratosis and generalized ichthyosis." (PMID 28774589, 2017).
keratosis (1 paper, 2024). A skin disorder consisting of hypertrophy of the stratum corneum of the skin. "For expanded gene families, we found three genes were associated with skeletal development and/or bone density (HNRNPH1, LIN28A, and TARP) and two genes (FTH1 and KDSR) were related to keratosis." (PMID 39092175, 2024).
leukemia (1 paper, 2025). A malignant (clonal) hematologic disorder, involving hematopoietic stem cells and characterized by the presence of primitive or atypical myeloid or lymphoid cells in the bone marrow and the blood. "In another study, exogenously added 3-ketosphinganine was cytotoxic for MV4-11 (biphenotypic leukemia) and MOLM13 (AML) cells, and these cells were also affected by knockout of KDSR, which elevated intracellular 3-ketosphinganine." (PMID 39859363, 2025).
ovarian carcinoma (1 paper, 2021). A malignant neoplasm originating from the surface ovarian epithelium. "Survival analysis showed that the high levels of SPHK1, KDSR, SMPD1, GALC, SMPD2, UGCG and DEGS1 were associated with poor prognosis of OS in patients with ovarian cancer, among which DEGS1 was the most significant (P = 3E-04)." (PMID 34488809, 2021).
cancer (7 papers, 2007 to 2025). A tumor composed of atypical neoplastic, often pleomorphic cells that invade other tissues. "When we focus on the molecular environment, a striking indication that predicts a poorer prognosis for PAAD patients is the increase in KDSR expression inside high-risk PAAD cancer tissues." (PMID 38028544, 2023). "KDSR and DESG1 are important molecules in the sphingosine synthesis pathway, which plays an important role in sphingolipid metabolism for the growth and metabolism of cancer cells." (PMID 36855810, 2023). "In the sensitive cell lines, knockout of KDSR induced the formation of irregular, distended subcellular structures and apoptosis (as well as ER stress, shown in later experiments), but not in the insensitive cancer lines and normal lines." (PMID 39859363, 2025). "Indeed, in cancer cells, but not in normal cells, the inhibition of KDSR induces the toxic accumulation of 3KDS, leading to ER dysfunction and loss of proteostasis." (PMID 36768427, 2023).
tumor (7 papers, 2014 to 2024). "Tsc10 is functionally homologous to 3-ketodihydrosphingosine reductase (FVT1), known to be active at the cytosolic face of the ER and implicated in tumor processes." (PMID 24868093, 2014). "However, similar to BCL6 and BCL2, KDSR is differentially expressed between tumor and normal paired FL samples (KS-test P < 0.001)." (PMID 28765546, 2017). "Additionally, KDSR and NEU1 in this pathway was found to be significantly upregulated along the trajectory indicating potential targets for the development of anti‐tumour strategies." (PMID 36855810, 2023).
infection (1 paper, 2025). The state of being infected such as from the introduction of a foreign agent such as serum, vaccine, antigenic substance or organism. "Interestingly, in the cell lines depleted for SPTLC1 or deficient for KDSR, a slightly increased number of inclusions was detected after infection with CTL2-cpoS::cat." (PMID 40794560, 2025).
KDSR also shares sentences with these, for which no sentence is quoted: steatosis (3 papers); Keratinization Disorders (2); skin disorder (2); central nervous system diseases (1); follicular lymphoma (1); geographic atrophy (1); Harlequin ichthyosis (1); Hepatosplenomegaly (1); keratinization (1); mental disorder (1); myeloma (1); Netherton syndrome (1).